SOAT1 (sterol O-acyltransferase 1)
Diseases named in the same sentence as SOAT1 in open-access papers (continued):
Sharing a sentence is not in itself a finding about the gene and the disease.
astrocytoma (6 papers, 2017 to 2024). "This could be an explanation for the higher SOAT1-expression in GBM compared to low-grade astrocytoma in the mentioned study." (PMID 35409086, 2022). "Here, we refined SOAT1-expression in GBM and IDH-mutant astrocytoma, CNS WHO grade 4 (HGA), and assessed the distribution of LD in these tumors." (PMID 35409086, 2022). "Higher SOAT1 expression has been demonstrated in GBM compared to astrocytoma of lower malignancy (CNS WHO grades 2–3), with absence of expression in pilocytic astrocytoma, CNS WHO grade 1, and control brains with cortical dysplasia." (PMID 35409086, 2022). "We therefore assessed SOAT1 expression by immunohistochemistry in tumor tissue from patients with GBM and IDH-mutant astrocytoma, CNS WHO grade 4 (HGA), using normal brain as a control that could also be relevant for the observed neurotoxic side effects of SOAT1 inhibitors such as mitotane." (PMID 35409086, 2022).
amyloid (5 papers, 2022 to 2025). "Since then, it has been shown that reducing ACAT1/SOAT1 activity by genetic manipulation or small molecule inhibition reduces amyloid pathology and rescues deficits seen in mouse models of AD." (PMID 36982602, 2023). "Blocking ACAT1/SOAT1 activity by genetic ablation or pharmacological inhibition has been shown to reduce amyloid pathology in mice by lowering levels of the amyloid precursor protein (APP) and its toxic product, Aβ." (PMID 36982602, 2023).
dementia (5 papers, 2018 to 2025). Loss of intellectual abilities interfering with an individual's social and occupational functions. "Humans ACAT1/SOAT1 genetic variant analyses also support the role of ACAT1 in modulating dementia susceptibility." (PMID 33841127, 2021).
lipid metabolism disorder (5 papers, 2018 to 2024). "Compared with the Control group, the mRNA expression of Srebf2, Scap, Hmgcr, Soat1, Npc1, Snai3, Twist1, Itgav, Vegfc, and Tgfbr1 has higher expression in model group, indicating that there is lipid metabolism disorder in model mice." (PMID 38724499, 2024).
schizophrenia (5 papers, 2018 to 2025). A major psychotic disorder characterized by abnormalities in the perception or expression of reality. "Interestingly, the remaining genes in which immobilization (Immo+FC) had induced changes in expression seem to be involved in immune response (Lbp and Lnc2), anxiety behavior and schizophrenia (Pde7b), corticosterone homeostasis, and steroid transportation (Lcn2 and Soat1)." (PMID 30705647, 2018).
squamous cell carcinoma (5 papers, 2016 to 2024). A carcinoma arising from squamous epithelial cells. "Runt-related transcription factor 1 promoted the expression of SOAT1 by binding to the promoter region of SOAT1 in squamous cell carcinomas." (PMID 35646697, 2022).
Cirrhosis (4 papers, 2019 to 2025). A chronic disorder of the liver in which liver tissue becomes scarred and is partially replaced by regenerative nodules and fibrotic tissue resulting in loss of liver function. "We did observe downregulation of the cellular cholesterol esterification enzyme, SOAT1 in LPS-stimulated whole blood from patients hospitalized with decompensated cirrhosis compared to healthy volunteers and with patients with refractory ascites having intermediate expression." (PMID 40126412, 2025).
gastric adenocarcinoma (4 papers, 2016 to 2021). "Furthermore, Kaplan-Meier plotter data also confirmed that high level of SOAT1 was associated with poor survival in patients with gastric adenocarcinoma patients." (PMID 34790132, 2021).
intestinal tumor (4 papers, 2021 to 2022). "Depletion of Soat1 attenuates spontaneous intestinal tumor development in ApcMin/+ mice." (PMID 34914638, 2022).
kidney injury (4 papers, 2020 to 2025). Trauma to the kidney. "We found that tubule-specific Pacs-2 deletion markedly aggravated lipid accumulation in tubular cells by increasing the expression of SOAT1 and then regulating lipid synthesis, uptake and efflux by SOAT1/SREBPs signaling, eventually resulting in worsening albuminuria excretion and kidney injury." (PMID 36138342, 2022).
coronary heart disease (3 papers, 2017 to 2022). "A study showed that the methylation level of SOAT1 in patients with coronary heart disease is significantly decreased." (PMID 35354120, 2022). "Therefore, we assume that SOAT1 gene and coronary artery disease might be associated." (PMID 31684966, 2019). "A study found that the methylation level of SOAT1 promoter is lower in patients with coronary heart disease and higher in patients with non-coronary heart disease." (PMID 35354120, 2022).
Cushing syndrome (3 papers, 2018 to 2022). Cushing's syndrome (CS) encompasses a group of hormonal disorders caused by prolonged and high exposure levels to glucocorticoids that can be of either endogenous (adrenal cortex production) or exogenous (iatrogenic) origin. "Regarding OS, Cushing’s syndrome (p = 0.013), an ENSAT 3/4 stage (p < 0.0001), a Weiss score > 6 (p < 0.0001), a Ki67 index > 10% (p < 0.0001), and strong SOAT1 protein expression (p = 0.007), were associated with reduced OS." (PMID 31963898, 2020).
dry eye (3 papers, 2021 to 2025). "Previously, changes in MG lipidomes induced by inactivation of critical genes of meibogenesis, such as Elovl3, Soat1, Awat2, Sdr16c5/Sdr16c6, and others were shown to cause MG dysfunction (MGD) and dry eye in experimental animals." (PMID 41373590, 2025). "The Soat1-null mice had clear manifestations of dry eye and MG dysfunction." (PMID 33557318, 2021).
hyperlipidemia (3 papers, 2011 to 2021). "To directly evaluate the role of Soat1 in hyperlipidemia, we constructed transgenic mice that expressed C3H Soat1 and crossed the mice with B6.apoE−/− mice for more than six generations." (PMID 22022387, 2011). "Human genetic studies indicate that Soat1 variants are associated with elevations in plasma concentrations of HDL cholesterol and apoA-I among subjects with hyperlipidemia." (PMID 22022387, 2011). "In the present study, we tested whether Soat1 was a QTL gene contributing to naturally occurring variation in plasma lipid levels, especially under the circumstances of hyperlipidemia, in mice." (PMID 22022387, 2011).
leukocytosis (3 papers, 2019 to 2022). "These global Soat1−/− mice were also characterized to have leukocytosis and an increase in bone marrow cell proliferation." (PMID 34436484, 2021). "Chang and colleagues bred Soat1 floxed mice and crossed them with LysM-Cre mice to generate myeloid-specific Soat1-deficient mice (Soat−M/−M), which did not have leukocytosis as seen in the global KO mice." (PMID 34436484, 2021).
lymph node metastasis (3 papers, 2021 to 2025). "qRT‐PCR analysis of patient SOAT1 mRNA levels demonstrated a similar trend, with higher expression levels in patients at clinical stages T3‐T4 and those with lymph node metastasis." (PMID 40135589, 2025). "When analyzing the correlation between SOAT1 expression levels and clinical‐pathological parameters, we found a statistically positive correlation with clinical stage (p < 0.0001) and lymph node metastasis (p < 0.0001)." (PMID 40135589, 2025). "The expression of sterol O-acyltransferase 1 (SOAT1), a protein associated with cholesterol synthesis, has been found to promote lipid synthesis and lymph node metastasis in GC." (PMID 38062450, 2023). "Taken together, these findings indicated that inhibition of SOAT1 suppresses lymphangiogenesis and that avasimibe has the potential therapeutic effect for GC patients with lymph node metastasis." (PMID 34790132, 2021).
memory impairment (3 papers, 2008 to 2022). "The deletion of Soat1 specifically causes memory impairment at remote time points." (PMID 18464936, 2008).
mesothelioma (3 papers, 2023 to 2025). A usually malignant and aggressive neoplasm of the mesothelium which is often associated with exposure to asbestos. "By intersecting high-risk genes with upregulated DEGs, we identified four key high-risk genes associated with mesothelioma: MPZL1, SOAT1, TACC3, and CYBRD1." (PMID 40223054, 2025). "Noteworthy observations included a significant infiltration of M1 macrophages and CD4 + T cells in mesothelioma, with genes SOAT1, MNDA, and ITGAM showing a positive correlation with the level of M1 macrophage infiltration." (PMID 40223054, 2025). "Additionally, we discovered that the genes SOAT1, TACC3, and NDRG2 are linked to the prognosis of mesothelioma patients." (PMID 40223054, 2025). "Since normal sample data were lacking for mesothelioma (MESO) and uveal melanoma (UVM), significant differences in SOAT1 expression between tumor and normal tissues were only compared in 24 cancers." (PMID 37304239, 2023). "Currently, there are no research reports on the roles of SOAT1, TACC3, and NDRG2 in mesothelioma." (PMID 40223054, 2025).
intestinal cancer (2 papers, 2022 to 2023). "Thus, we detected the SOAT1 protein levels in ApcMin/+ mice to characterize the possible interaction between SOAT1 and Apc mutant induced spontaneous intestinal cancer." (PMID 34914638, 2022). "Here, we report that ceramide and sterol O-acyltransferase 1 (SOAT1) have roles in both spontaneous and chemical-induced intestinal cancers." (PMID 34914638, 2022). "Finally, the SOAT1 inhibitor (avasimibe) showed significant levels of therapeutic effects on both AOM/DSS-induced and ApcMin/+ spontaneous intestinal cancer." (PMID 34914638, 2022). "Our above results showed that SOAT1 was highly expressed in CRC of both mice and humans and that deletion of SOAT1 could significantly inhibit the growth of both AOM/DSS-induced and spontaneous intestinal cancer in ApcMin/+ mice." (PMID 34914638, 2022).
Adrenal Tumors (1 paper, 2020). "Strong SOAT1 protein expression was significantly more frequent in cortisol-producing ACCs, in patients with more advanced disease stage at diagnosis (according to the European Network for the Study of Adrenal Tumors (ENSAT) staging system), and in carcinomas exhibiting a higher Ki67 index." (PMID 31963898, 2020). "Strong SOAT1 protein expression correlated with features of high aggressiveness in ACC, such as excessive tumor cortisol secretion (p = 0.01), an advanced disease stage [European Network for the Study of Adrenal Tumors (ENSAT) staging system 3 and 4 (p = 0.011)] and a high Ki67 index (p = 0.002)." (PMID 31963898, 2020).
gallbladder cancer (1 paper, 2025). "In a gallbladder cancer research, the expression of SOAT1 was found statistically significant with LN metastasis and TNM stages." (PMID 40135589, 2025).
hyperalphalipoproteinemia (1 paper, 2023). An autosomal dominant genetic condition caused by mutation(s) in the CETP gene, encoding cholesteryl ester transfer protein. "SOAT1 as a negative predictor of HDL-C level may be associated with the increase in intracellular free cholesterol pool available for efflux at hyperalphalipoproteinemia in controls." (PMID 37623250, 2023).
leprosy (1 paper, 2024). Leprosy is a chronic infectious disease affecting primarily the skin and peripheral nervous system. "In the E-MTAB-10318 dataset, APOE, CYP27A1, FADS1, and SOAT1 showed higher expression levels in leprosy compared to the control group." (PMID 38273053, 2024).
small intestine tumor (1 paper, 2022). "All together, these data suggested that depletion of Soat1 attenuated spontaneous colon and small intestine tumor development of ApcMin/+ mice." (PMID 34914638, 2022).
testicular germ cell tumor (1 paper, 2021). A germ cell tumor arising from the testis. "We further examined mRNA expressions of SOAT1 vs. SOAT2 in liver hepatocellular carcinoma (LIHC) and testicular germ cell tumors (TGCT) tissues; the result revealed that SOAT1 expression remained higher than SOAT2." (PMID 34052835, 2021).
cancer (1,906 papers, 1995 to 2026). A tumor composed of atypical neoplastic, often pleomorphic cells that invade other tissues. "SOAT1 plays a critical role in cholesterol metabolism and has been implicated in various cancers, although its specific mechanisms in OSCC are poorly understood." (PMID 40135589, 2025). "Previous studies have demonstrated that elevated SOAT1 expression is linked to poor prognosis in various cancers, including prostate and pancreatic cancer." (PMID 40687983, 2025). "Compelling evidence have implicated that targeting SOAT1 is a promising therapeutic strategy for cancer management." (PMID 37409263, 2023). "As reported in previous studies, deregulated SOAT1 is associated with tumor aggressiveness and therapy resistance, indicating poor prognosis in different kinds of cancers." (PMID 37409263, 2023). "SOAT1 has also been found to be associated with the progression of atherosclerosis, Alzheimer’s disease, and several cancers." (PMID 37304239, 2023). "Many studies have implicated that SOAT1 plays a vital role in cancer initiation and progression and is an attractive target for novel anticancer therapy." (PMID 37409263, 2023). "Survival analyses for each cancer were performed to examine the association between SOAT1 expression and prognosis." (PMID 37304239, 2023). "In recent years, several studies have indicated that cholesterol esterification is deregulated in cancers, and SOAT1 has received increasing attention for its association with cancer." (PMID 37409263, 2023). "A gene co-expression analysis was further used to study the associations between SOAT1 expression levels and immune-related genes in pan-cancer." (PMID 37304239, 2023). "We systematically screened the expression of 111 rate-limiting enzymes in TCGA database, and identified SOAT1 expression level is significantly increased in cancer tissues and closely associated with the poor outcome of GC patients." (PMID 34790132, 2021). "Reactivation of NLRP3 inflammasome could recover impaired cancer cell migration and invasion abilities caused by SOAT1 knockdown." (PMID 40135589, 2025). "SOAT1 expression is significantly elevated in most cancers and is strongly correlated with prognosis." (PMID 40969353, 2025). "RNA sequencing analysis revealed that NLRP3 is a downstream regulated by SOAT1, with NLRP3 inflammasome reactivation having recovered cancer malignancy inhibited by SOAT1 knockdown." (PMID 40135589, 2025). "When we reactivated the NLRP3 inflammasome in OSCC cells, the malignancy inhibited by SOAT1 knockdown was recovered, confirming that NLRP3 inflammasome as the downstream of SOAT1 play a vicious role for cancer progression." (PMID 40135589, 2025). "SOAT1 plays a critical role not only in metabolic diseases and cancer but also potentially in growth development and bone health." (PMID 40969353, 2025). "Among these, SQLE and SOAT1 stand out as the most robust predictors and potential therapeutic targets, emphasizing the critical role of cholesterol metabolic reprogramming in cancer progression." (PMID 40707931, 2025). "Specifically, the role of SOAT1 in cholesterol esterification has been attributed to cancer progression by increasing cancer lipid droplets." (PMID 40707931, 2025). "We obtained 30 paired samples comprising OSCC cancer and adjacent tissues and RT-qPCR verified that SOAT1 had higher expression in cancer compared to adjacent tissues." (PMID 38993570, 2024). "SOAT1, located in the endoplasmic reticulum of cells and catalyzes the formation of cholesteryl esters 41, is up-regulated in various cancers." (PMID 38993570, 2024). "In this review, we provide an overview of the mechanism and regulation of SOAT1 in cancer and summarize the updates of anticancer therapy targeting SOAT1." (PMID 37409263, 2023). "After analyzing SOAT1 gene expression in pan-cancer databases, we next evaluated SOAT1 protein levels." (PMID 37304239, 2023).
cancer (continued). "Our study found that SOAT1 significantly correlated with the infiltration of T cells and other immune cells in various cancer types." (PMID 37304239, 2023). "In this review, we mainly discuss the cholesterol metabolism centered on SOAT1 and mechanisms that regulate SOAT1 expression in cancers." (PMID 37409263, 2023). "Herein, we aimed to expound the predictive value and the potential biological functions of SOAT1 in pan-cancer." (PMID 37304239, 2023). "We also validated the prognostic value of SOAT1 in various cancers; hence, it is necessary to further study the relationship between TME and SOAT1 levels in different cancers." (PMID 37304239, 2023). "SOAT1 expression was significantly increased in most cancers and showed a distinct correlation with prognosis." (PMID 37304239, 2023). "Cancers with the most significant correlation between the types of infiltrating immune cells and SOAT1 expression levels were then analyzed." (PMID 37304239, 2023). "SOAT1 plays an important role in maintaining cellular cholesterol homeostasis by meeting the requirement of cancer cells for cholesterol." (PMID 37409263, 2023). "Raw data related to SOAT1 expression in 33 different types of cancer were acquired from The Cancer Genome Atlas (TCGA) and Genotype-Tissue Expression (GTEx) databases." (PMID 37304239, 2023). "First, even though bioinformatic analyses have provided some relevant insights into SOAT1 in pan-cancer, in vitro or in vivo experiments are required to validate these findings." (PMID 37304239, 2023). "Here, we conducted a pan-cancer study to evaluate SOAT1 levels and their relationship with prognosis using TCGA, GTEx, and cBioPortal databases." (PMID 37304239, 2023). "Meanwhile, combined therapy of SOAT1 inhibitor avasimibe plus programmed cell death 1 antibody was found to have an enhanced therapeutic effect in controlling some cancer growth in mice." (PMID 34914638, 2022). "The pan-cancer analysis of the correlation between SOAT1 expression and 28 TILs is displayed via a heatmap." (PMID 35646697, 2022). "Although the mechanisms driving the high SOAT1 expression in tumors remain elusive, targeting SOAT1 has proved to be a promising therapeutic strategy for managing cancers." (PMID 33637695, 2021). "Compelling evidence implicate targeting SOAT1 as a promising therapeutic strategy for cancer management." (PMID 33637695, 2021). "The genetic silencing of SOAT1/ACAT1 or the pharmacologic blocking of its activity suppresses tumor growth in several cancer xenograft models." (PMID 35198567, 2021). "Since there is a known inhibitor of SOAT1, mitotane, we finally selected and validated the anti-cancer effect of SOAT1 in a widely used ccRCC cell line Caki-1." (PMID 34258555, 2021). "The impact of SOAT1 overexpression on cancer prognosis has already been demonstrated in several malignancies, suggesting a pivotal role of lipid metabolism and lipid droplet formation in tumor progression and aggressiveness." (PMID 31963898, 2020). "Additionally, enzymes such as squalene epoxidase (SQLE) and sterol O-acyltransferase 1 (SOAT1) play significant roles in cholesterol biosynthesis and esterification, respectively, and their dysregulation has been associated with cancer progression." (PMID 40707931, 2025). "This suggests that high SOAT1 expression could be a common characteristic across multiple types of cancer and may serve as a potential prognostic biomarker and therapeutic target for several tumours, including HCC." (PMID 40687983, 2025). "Recent studies have found that SOAT1 was upregulated in many cancers." (PMID 40135589, 2025). "Recent research has highlighted the involvement of SOAT1 in cancers." (PMID 40135589, 2025). "SOAT1, a critical enzyme in lipid metabolism, holds high prognostic value in various cancers." (PMID 38993570, 2024).